MTOR (mechanistic target of rapamycin kinase)
Diseases named in the same sentence as MTOR in open-access papers (continued):
Sharing a sentence is not in itself a finding about the gene and the disease.
cancer (continued). "Since KRAS is frequently mutated in human cancer, many cancers will have constitutive mTOR activity, but may not be sensitive to rapamycin as they will have Raf/MEK/ERK pathway activation." (PMID 23085539, 2012). "Thus, the repressive effect of curcumin on mTOR further supports the notion that curcumin might repress Wnt activity in cancer cells." (PMID 22253696, 2012). "Reduced AKT/mTOR signaling paralleled by an increase in lysosomal activity points towards the activation of a specific catabolic process, called autophagy, which is known to be a survival mechanism frequently utilized by cancer cells to adapt to metabolic and cellular stress." (PMID 23110223, 2012). "However, a more recent study using a retro-inhibition approach found that HNSCC cells and not the tumor microenvironment as the target for rapamycin activity and that the anti-angiogenic effect is a likely downstream consequence of mTOR inhibition in cancer cells." (PMID 23185335, 2012). "MTOR is a central regulator in cellular processes (metabolism, survival, proliferation) upon which tumor cells depend and there are growing data indicating that many cancers present alteration upstream and downstream of mTOR leading to this pathway abnormal activation." (PMID 22761648, 2012). "The inhibition of mTOR by rapamycin, or calorie restriction, has been shown to extend lifespan and delays tumorigenesis in several experimental models suggesting that rapamycin may be used for cancer prevention." (PMID 23117593, 2012). "In addition to a major role of the AMPK/mTOR pathway in regulation of intracellular and whole body metabolism, recent findings point to its potential involvement in controlling proliferation, survival, and death of cancer cells." (PMID 22496691, 2012). "Thus, at least 3 mechanisms of how mTOR-driven aging can contribute to cancer." (PMID 22267462, 2011). "Targeting the PI3K/PTEN/Akt/mTOR pathway may prove effective therapy in a variety of cancers." (PMID 21881167, 2011). "Moreover, metformin may exhibit direct inhibitory effects on cancer cells by inhibiting mammalian target of rapamycin (mTOR) signaling and protein synthesis." (PMID 21470407, 2011). "Therefore, the inhibition of mTOR is a potential treatment for certain forms of cancer." (PMID 21763421, 2011). "Targeting the PI3K/PTEN/Akt/mTOR pathway may prove effective in various cancer therapies." (PMID 21730367, 2011). "But much of the attention paid of late to eIF4E biology as it pertains to cancer, especially from oncologists and pharmaceutical companies, relates to the anti-neoplastic potential of the macrolide rapamycin (and its analogs) and its cellular target, the master kinase mTOR." (PMID 21378410, 2011). "Intriguingly, compounds activating autophagy via the AMP-activated protein kinase (AMPK)/mammalian target of rapamycin (mTOR) pathway, including resveratrol and rapamycin, exert protective effects in models of cardiovascular disease, but cytotoxic or cytostatic effects in cancer models." (PMID 21635740, 2011). "Although these clinical trials may challenge the relevance of targeting mTOR in cancer therapy, recent findings have demonstrated the complex consequences of blocking mTOR in cancer cells and have helped develop new therapeutic strategies aimed to improve the anticancer efficacy of mTOR inhibitors." (PMID 24212820, 2011). "The formation of the rapamycin-sensitive mTORC1 complex (consisting of mTOR, regulatory“associated protein of mTOR [Raptor], DEPTOR and mLST8) in certain cancer cells that overexpress activated Akt may be altered in comparison to cells that do not overexpress Akt." (PMID 21411864, 2011). "Because mTOR inhibitors have been utilized for cancer therapy, and only modest or unremarkable success has been achieved in some clinical trials, it is urgent to investigate the long-term effects of transient mTOR treatment on tumor re-emergence and malignant outcome." (PMID 22145042, 2011).
cancer (continued). "Different data provide evidence that the mTOR pathways receive stimulatory signals from Ras, and, ultimately, these pathways drive tumorigenesis through the coordinated phosphorylation of proteins that directly regulate protein synthesis, cell-cycle progression, and cancer development." (PMID 21904669, 2011). "Thus, 4E-BP1 appears to be an important target of mTOR that influences cancer growth." (PMID 24212820, 2011). "Taken together, these results provide an important insight into how cAMP signals to mTOR and down-regulates its activity, which may lead to the identification of novel drug targets to inhibit mTOR that could be used for the treatment and prevention of human diseases such as cancer." (PMID 21763421, 2011). "However, mTOR inhibitors have proved less successful in cancer clinical trials than might be hoped from the importance of the molecular pathways involved." (PMID 21320304, 2011). "However, in vitro observations were based on anti-cancer radiation doses, as a consequence the impact of mTOR-inhibition together with the relative low radiation dose used in TLI may not be of clinical importance." (PMID 20078889, 2010). "Thus, our results suggest that activation of Akt/mTOR pathway is a common event in TRAIL resistant cancer cell lines and that this pathway may be important in TRAIL resistance." (PMID 20419107, 2010). "Furthermore, there is evidence that metformin may have insulin independent direct effects of cancer cells, acting as a mammalian target of rapamycin (mTOR inhibitor)." (PMID 21084729, 2010). "Additionally, abnormally activated mTOR may give cancer cells a competitive growth advantage by increasing production of the core enzymes necessary for glycolysis, which enables cancer cells to survive and grow even under hypoxic conditions." (PMID 21584218, 2010). "Therefore, we hypothesize that, in addition to its effects on GI motility, MNTX might have clinical utility by potentially lowering the therapeutic doses of mTOR inhibitors in the treatment of various diseases requiring angiogenesis including cancer." (PMID 20298531, 2010). "Furthermore, a potential 2-O-Bn-InsP5-mediated inhibition of mTORC2 would also increase the inhibitory activity towards Akt, by preventing its Ser473 phosphorylation, indicating that 2-O-Bn-InsP5 represents a useful compound to be tested in cancer types specifically dependent on mTOR activation." (PMID 20051961, 2010). "Besides these mutations we have also identified several mutated cancer drug targets or genes that are associated with treatment outcome, including BRAF, KRAS, FGFR2 and MTOR, which might help to choose optimal drug combinations." (PMID 21203531, 2010). "Based on preclinical findings, mTOR inhibitors may be more efficacious when used in rational combination with other cancer regimens with activities supplemental to and/or influenced by mTOR activity, such as DNA-damaging and hormonal agents, oncogene inhibitors, and other targeted therapies." (PMID 21584218, 2010). "Thus, early steps of tumorigenesis in many mouse models of cancer are reliant on mTOR activation." (PMID 19330036, 2009). "Consequently, inhibitors of mTOR, including temsirolimus, everolimus, and ridaforolimus (formerly deforolimus) have been developed and assessed for their safety and efficacy in patients with cancer." (PMID 19860903, 2009). "Thus, the inhibition of mTOR may inhibit abnormal cell proliferation, tumour angiogenesis, and abnormal cell metabolism and potentially enhance the efficacy of other cancer treatments." (PMID 19128503, 2009).
cancer (continued). "The distinct expression of mTOR and p-P70S6K could be employed to differentiate the intestinal- and diffuse-type carcinomas and underlay the molecular mechanism about the differentiation of both carcinomas." (PMID 20003385, 2009). "Furthermore, targeting the glycolytic pathway in combination with mTOR inhibition may also be useful in cases where DNA-damaging agents are less efficient in inhibiting growth and promoting apoptosis of cancer cells." (PMID 16404421, 2006). "Thus, inhibition of mTOR may have direct effects on cancer cell proliferation and survival, indirect effects via inhibition of HIF-1α, thus reducing tumour-elicited VEGF, direct effects on vascular endothelial cells, or vascular smooth muscle cells." (PMID 16953237, 2006). "Adiponectin activates cellular functions and pathways via peroxisome proliferator‐activated receptor and AMPK that inhibit mTOR, PI3K, and STAT3 (the last via suppressing cytokine signaling 3), inhibiting cancer cell proliferation and progression." (PMID 41450167, 2026). "Overall, this is the first study to demonstrate that PEC exerted potent anti-cancer effects against CC by concurrently inducing autophagy and apoptosis through targeted inhibition of the AKT/mTOR pathway." (PMID 41924135, 2026). "In this study, we performed in silico and in vitro analyses to assess the antitumor potential of two pyrazino-pyrido[2,3-d]pyrimidine-5,7-dione Series (A and B) across various cancer cell lines, focusing on possible PI3K/AKT/mTOR inhibition." (PMID 41677168, 2026). "Key oncoproteins, such as LANA, vCyc, vFLIP, and vGPCR, activate cancer hallmarks, as sustained proliferation, immune evasion, angiogenesis, and resistance to cell death, by modulating pathways such as PI3K/AKT/mTOR and NF-κB." (PMID 41563473, 2026). "The results of these lines of experimentation suggest that for a subset of cancers, inhibition of PI3K/AKT/mTOR signaling can dramatically increase the efficacy of kinesin-5 inhibitors in driving mitotic cell death." (PMID 41602832, 2026). "Mechanistically, loss of PAK1 promoted mRNA decay and inhibited the expression of CD44, SAA1, MTOR, RPS6KB1, and EIF4G1, the factors involved in tumorigenesis in many cancers." (PMID 41459112, 2026). "Just around one hundred of these genes are similarly upregulated or downregulated in all mutant cell lines and relate to transcriptional misregulation in cancer, including MAPK and mTOR signalling amongst other enriched KEGG pathways." (PMID 41266617, 2026). "Pathway analysis highlighted the connection of SFXN1 to key signaling cascades, including the mTOR, PI3K-Akt, and HIF-1 pathways, which are pivotal in cancer progression, metabolism, and the hypoxia response." (PMID 41399448, 2026). "Given the pathway's significant role in disease progression, particularly cancer, targeting the AKT/mTOR axis holds considerable therapeutic promise." (PMID 41774454, 2026). "Glutamine is used by cancer cells for amino acid biosynthesis, production of NADPH, and nucleotides, as well as promotion of mTOR activation and downstream protein translation." (PMID 41131959, 2026). "The mTOR pathway is interconnected with other signaling networks such as PI3K/AKT and AMPK, playing a pivotal role in cell growth regulation and cancer progression." (PMID 40055330, 2025). "We continued our work on PKC, which became more focused on defining the function of PKCα in cancer signaling, especially relating it to the AKT/mammalian target of rapamycin (mTOR) pathway." (PMID 41390057, 2025). "PDAC cancer stem cell markers including CD44, MET, CD133, FUT4, ACVR1, mTOR, and KLF4 were positively related to IARS2 expression." (PMID 40092487, 2025). "By modulating critical pathways like AKT/mTOR in autophagy and NRF2 in ferroptosis, UA exhibits substantial anti-cancer effects across various types of cancer." (PMID 40490812, 2025).
cancer (continued). "By targeting multiple molecular pathways, including Wnt/β-catenin, PI3K/Akt/mTOR, JAK/STAT3, MAPK, NF-κB, and Notch, curcumin suppresses cancer growth and induces apoptosis." (PMID 41020838, 2025). "The current work revealed a significant downregulation of PI3K, AKT, mTOR, and GSK-3β mRNA levels in cancer cells treated with GLE and GNPs compared to the untreated group, with a significant downregulation in GNPs compared to its free counterpart." (PMID 41039321, 2025). "Cell migration‐related differential genes were mainly enriched in proteoglycans in cancer-related pathway, EGFR tyrosine kinase-related pathway, mTOR signaling pathway, and complement and coagulation cascades-related pathway, etc.." (PMID 41497806, 2025). "For instance, Lanatoside C induces G2/M cell cycle arrest and inhibits cancer cell growth by weakening the MAPK, Wnt, JAK-STAT, and PI3K/AKT/mTOR signaling pathways." (PMID 40041495, 2025). "The AKT/mTOR/HIF-1α signaling pathway is crucial in promoting glycolysis and lactation, thus contributing to the “metabolic reprogramming” of cancer cells." (PMID 40989165, 2025). "These shared mechanisms suggest opportunities for cross-cancer therapeutic strategies, with the PI3K/mTOR pathway already showing promise through inhibitors such as BKM120 and BYL719, which act as radiosensitizers in OSCC." (PMID 41244916, 2025). "It has been shown that TA interferes with several critical pathways involved in cancer development and progression, including NF-κB, PI3K/AKT, ERK1/2, Wnt/β-catenin, JAK/STAT, RAS/RAF/mTOR, TGF-β1/TGF-β1R axis, VEGF/VEGFR signaling and CXCL12/CXCR4 axis." (PMID 41009634, 2025). "A key regulator of autophagy is the mammalian target of the rapamycin (mTOR) pathway, which is activated downstream of PI3K-AKT, a pathway commonly dysregulated in cancer." (PMID 39863145, 2025). "Recent clinical trials have introduced several drugs and strategies based on these principles, such as mTOR inhibitors and TGF‐β inhibitors, which have shown promising efficacy in treating cancer patients." (PMID 40959206, 2025). "Aberrant activation of mTOR is frequently observed in tumorigenesis, leading to the buildup of HIF-1α and subsequent stimulation of cancer cell growth." (PMID 39965249, 2025). "The enrichment study identified significant enrichment in pathways, including Pathways in Cancer, the PI3K-Akt signaling pathway, the mTOR signaling pathway, the TGF-β signaling pathway, and the specific HCC pathway." (PMID 40074445, 2025). "Several cancer-relevant signaling pathways, including PPAR, MAPK, Ras, and mTOR signaling, were also significantly enriched." (PMID 41516087, 2025). "Cancer cells can develop chemoresistance by altering key signaling cascades, notably the EGFR/PI3K/PTEN/Akt/mTOR axis." (PMID 41303548, 2025). "In summary, we identify PVT1 as a complex molecular hub that orchestrates the interplay between MYC, mTOR, AKT, and RAS signaling in cancer." (PMID 40027648, 2025). "Focusing on 14-3-3ζ which was reported to be highly expressed in various cancers, we found that BA also inhibited the binding of 14-3-3ζ to TSC2, Rictor, Raptor, mTOR, FOXO1, FOXO3a, and STAT3." (PMID 40316727, 2025). "When this inhibitory role is disrupted, RTK activation triggers the phosphorylation of downstream components, initiating multiple signaling cascades including PI3K-Akt-mTOR and JAK-STAT pathways, which are frequently dysregulated in cancer." (PMID 40885971, 2025). "Key signaling pathways, such as mTOR and AMPK, become dysregulated, further compromising T cell responses to cancer." (PMID 40153576, 2025).
cancer (continued). "To elucidate the effects of various treatments on key signaling pathways involved in cancer cell proliferation and apoptosis, we analyzed the expression levels of Akt, PI3K, mTOR, and Caspase-3 in A549 and MDA-MB-231 cell lines." (PMID 40179064, 2025). "For instance, in the comparison between PCa tumor and normal samples, DiCE identified 61 cancer fitness genes, including MYC, CCNA2, PLK1, PTTG1, EPCAM, and MTOR, that were overlooked by typical DEA but are well-documented contributors to PCa progression." (PMID 40626556, 2025). "There was plenty of evidence that CuNPs had anti-cancer potential; this has been shown by the effect of the molecules on the PI3K/AKT/mTOR pathway, which was one of the pathways crucial for cancer survival." (PMID 39787250, 2025). "Although previous studies have developed nanostructures for stimulating ferroptosis in cancer, their impact on the PI3K/AKT/mTOR pathway requires better understanding." (PMID 40740483, 2025). "Through gene set enrichment analysis (GSEA), we discovered that TMEM45A promotes cancer cells resistance to CDK4/6i and glycolysis by activating the AKT/mTOR signaling pathway." (PMID 39910045, 2025). "Due to the frequent activation of the PI3K/AKT/mTOR pathway in a variety of tumor types, it has become an important target for cancer therapies, and a variety of drugs targeting PI3K, AKT, or mTOR are currently on the market or under development." (PMID 40507124, 2025). "Results from in vitro studies show that AP effectively inhibits cancer cell growth and leads to the death of cancer cells in a dose- and time-dependent manner, via apoptosis and autophagy through the inhibition of the PI3K/Akt/mTOR and RAF/MEK/ERK pathways." (PMID 41228311, 2025). "By delivering rapamycin directly to cancer cells, Rapa-PLGA NPs effectively downregulated oncogenic genes including mTOR, HIF-α, BCL-2, and ABCC1, while simultaneously upregulating pro-apoptotic and stress response genes such as FOXO1 and MAPK." (PMID 40604062, 2025). "In addition, several miRNAs have been found in the host serum For instance, miR-184 may control the metastasis in triple-negative breast cancer by targeting the AKT/mammalian/mechanistic target of rapamycin (mTOR) pathway to cancer cell proliferation, invasion, and migration." (PMID 40918450, 2025). "This association has been confirmed experimentally with the use of rapamycin, an inhibitor of mTOR, effectively inhibiting HIF-1α accumulation and its subsequent transcriptional activity in hypoxic PC-3 cancer cells." (PMID 39965249, 2025). "The expression profiles of mTOR, MYC and RAS, which are important signaling pathways in cancer progression, were examined at the mRNA level." (PMID 40566531, 2025). "Among the key signaling pathways in cancer, the phosphatidylinositol-3-kinase (PI3K)/protein kinase B (AKT)/mammalian target of rapamycin (mTOR) cascade plays a pivotal role in regulating cellular survival, and apoptosis." (PMID 41039321, 2025). "LncRNAs are also the regulatory molecules in cancer-related pathways such as Hedgehog, Wnt, Notch, PI3K/AKT/mTOR." (PMID 40265013, 2025). "Upon activation, they promoted cancer cell proliferation and prevented apoptosis via PI3K/Akt/mTOR signaling with increased protein levels of MYC and HIF1α and stimulation of the Warburg effect." (PMID 39714760, 2025). "The mTOR pathway, which is a component of the PI3K/Akt/mTOR signalling axis and is frequently used by cancer cells to develop drug resistance, appears to be inhibited in this result." (PMID 40427522, 2025). "As expected, gene set enrichment analysis (GSEA) of dormant cancer cells revealed a decreased enrichment of cell cycle mediators including targets of E2F and MYC, as well as mTOR signaling." (PMID 40568095, 2025).